NPPA (natriuretic peptide A)
Description:
[Atrial natriuretic peptide]: Hormone that plays a key role in mediating cardio-renal homeostasis, and is involved in vascular remodeling and regulating energy metabolism. Acts by specifically binding and stimulating NPR1 to produce cGMP, which in turn activates effector proteins, such as PRKG1, that drive various biological responses. Regulates vasodilation, natriuresis, diuresis and aldosterone synthesis and is therefore essential for regulating blood pressure, controlling the extracellular fluid volume and maintaining the fluid-electrolyte balance. Also involved in inhibiting cardiac remodeling and cardiac hypertrophy by inducing cardiomyocyte apoptosis and attenuating the growth of cardiomyocytes and fibroblasts. Plays a role in female pregnancy by promoting trophoblast invasion and spiral artery remodeling in uterus, and thus prevents pregnancy-induced hypertension (By similarity). In adipose tissue, acts in various cGMP- and PKG-dependent pathways to regulate lipid metabolism and energy homeostasis. This includes up-regulating lipid metabolism and mitochondrial oxygen utilization by activating the AMP-activated protein kinase (AMPK), and increasing energy expenditure by acting via MAPK11 to promote the UCP1-dependent thermogenesis of brown adipose tissue. Binds the clearance receptor NPR3 which removes the hormone from circulation. [Long-acting natriuretic peptide]: May have a role in cardio-renal homeostasis through regulation of natriuresis, diuresis, vasodilation, and inhibiting aldosterone synthesis. In vitro, promotes the production of cGMP and induces vasodilation. May promote natriuresis, at least in part, by enhancing prostaglandin E2 synthesis resulting in the inhibition of renal Na+-K+-ATPase. However reports on the involvement of this peptide in mammal blood volume and blood pressure homeostasis are conflicting; according to a report, in vivo it is not sufficient to activate cGMP and does not inhibit collecting duct transport nor effect diuresis and natriuresis (By similarity). Appears to bind to specific receptors that are distinct from the receptors bound by atrial natriuretic peptide and vessel dilator. Possibly enhances protein excretion in urine by decreasing proximal tubular protein reabsorption. [Vessel dilator]: May have a role in cardio-renal homeostasis through regulation of natriuresis, diuresis, and vasodilation. In vitro, promotes the production of cGMP and induces vasodilation. May promote natriuresis, at least in part, by enhancing prostaglandin E2 synthesis resulting in the inhibition of renal Na+-K+-ATPase. However reports on the involvement of this peptide in mammal blood volume and blood pressure homeostasis are conflicting; according to a report it is not sufficient to activate cGMP and does not inhibit collecting duct transport nor effect diuresis and natriuresis. Appears to bind to specific receptors that are distinct from the receptors bound by the atrial natriuretic and long-acting natriuretic peptides. Possibly functions in protein excretion in urine by maintaining the integrity of the proximal tubules and enhancing protein excretion by decreasing proximal tubular protein reabsorption. [Kaliuretic peptide]: May have a role in cardio-renal homeostasis through regulation of diuresis and inhibiting aldosterone synthesis. In vitro, promotes the production of cGMP and induces vasodilation. May promote natriuresis, at least in part, by enhancing prostaglandin E2 synthesis resulting in the inhibition of renal Na+-K+-ATPase. May have a role in potassium excretion but not sodium excretion (natriuresis). Possibly enhances protein excretion in urine by decreasing proximal tubular protein reabsorption. [Urodilatin]: Hormone produced in the kidneys that appears to be important for maintaining cardio-renal homeostasis. Mediates vasodilation, natriuresis and diuresis primarily in the renal system, in order to maintain the extracellular fluid volume and control the fluid-electrolyte balance. Specifically binds and stimulates cGMP production by renal transmembrane receptors, likely NPR1. Urodilatin not ANP, may be the natriuretic peptide responsible for the regulation of sodium and water homeostasis in the kidney. [Auriculin-D]: May have a role in cardio-renal homeostasis through regulation of natriuresis and vasodilation. In vivo promotes natriuresis and in vitro, vasodilates renal artery strips. [Auriculin-B]: May have a role in cardio-renal homeostasis through regulation of natriuresis and vasodilation. In vivo promotes natriuresis and in vitro, vasodilates renal artery strips. [Auriculin-A]: May have a role in cardio-renal homeostasis through regulation of regulation of natriuresis and vasodilation. In vivo promotes natriuresis. In vitro, vasodilates intestinal smooth muscle but not smooth muscle strips. [Atriopeptin-2]: May have a role in cardio-renal homeostasis through regulation of natriuresis and vasodilation. In vivo promotes natriuresis. In vitro, selectively vasodilates intestinal and vascular smooth muscle strips. [Atriopeptin-1]: May have a role in cardio-renal homeostasis through regulation of natriuresis and vasodilation. In vivo promotes natriuresis. In vitro, selectively vasodilates intestinal smooth muscle but not vascular smooth muscle strips.
Synonyms: CDD; ANP; ANF; PND; ATFB6; ATRST2; CDD-ANF; CDP
Tractability: Small molecule: it belongs to a druggable protein family. Antibody: UniProt places it where antibodies can reach, with high confidence; its Gene Ontology location is reachable by antibodies, with high confidence; UniProt predicts a signal peptide or a membrane-spanning region. PROTAC: a small molecule that binds it is known.
Target class: Secreted protein
Gene: Protein-coding gene on chromosome 1 (11,845,709 to 11,848,345, reverse strand). Ensembl gene ENSG00000175206.
Subcellular location: Secreted (Long-acting natriuretic peptide); Secreted (Vessel dilator); Secreted (Kaliuretic peptide); Secreted (Urodilatin); Secreted (Atrial natriuretic peptide); Perikaryon; Cell projection; Secreted (Atriopeptin-3)
Pathways (Reactome):
Gene expression (Transcription): YAP1- and WWTR1 (TAZ)-stimulated gene expression
Metabolism of proteins: Amyloid fiber formation
Muscle contraction: Physiological factors
Gene Ontology:
Molecular function: hormone receptor binding; neuropeptide hormone activity; neuropeptide receptor binding; protein binding; signaling receptor binding; hormone activity
Biological process: cGMP biosynthetic process; negative regulation of JUN kinase activity; neuropeptide signaling pathway; positive regulation of cardiac muscle contraction; positive regulation of heart rate; positive regulation of potassium ion export across plasma membrane; protein folding; receptor guanylyl cyclase signaling pathway; regulation of atrial cardiac muscle cell membrane repolarization; regulation of blood pressure; aortic valve morphogenesis; cardiac conduction system development; female pregnancy; negative regulation of systemic arterial blood pressure; regulation of calcium ion transmembrane transport via high voltage-gated calcium channel; response to muscle stretch; cell growth involved in cardiac muscle cell development; cellular response to angiotensin; cellular response to glucose stimulus; cellular response to hydrogen peroxide; cellular response to mechanical stimulus; cGMP metabolic process; negative regulation of blood pressure; negative regulation of cell growth; negative regulation of collecting lymphatic vessel constriction; and 5 more
Cellular component: extracellular region; perikaryon; protein-containing complex; cytoplasm; brush border; glycinergic synapse; mast cell granule; perinuclear region of cytoplasm
Genetic constraint (gnomAD): Loss-of-function variants: 10 observed, 13.03 expected, observed/expected ratio (o/e) 0.77, 90% interval 0.47 to 1.3. The upper end of that interval is the gene's LOEUF score, 1.3, which puts it in group 5 of 6, group 1 being the genes least tolerant of losing a copy. Missense variants: 207 observed, 198.39 expected, observed/expected ratio (o/e) 1.04, 90% interval 0.93 to 1.17. Synonymous variants: 85 observed, 83.8 expected, observed/expected ratio (o/e) 1.01, 90% interval 0.85 to 1.22.
Gene-disease validity (ClinGen):
ClinGen rates the evidence that NPPA causes each of these diseases.
dilated cardiomyopathy (autosomal recessive): No Known Disease Relationship. Cardiomyopathy which is characterized by dilation and contractile dysfunction of the left and right ventricles.
Homologues: Orthologues: chimpanzee NPPA (100% identical), macaque NPPA (94% identical), pig NPPA (87% identical), guinea pig NPPA (84% identical), dog NPPA (83% identical), rabbit NPPA (83% identical), rat Nppa (81% identical), mouse Nppa (80% identical), zebrafish nppa (24% identical). Paralogues in human: NPPB (24% identical).
Diseases named in the same sentence as NPPA in open-access papers:
NPPA is named in the same sentence as 266 diseases in open-access papers, as found by Europe PMC text mining. Sharing a sentence is not in itself a finding about the gene and the disease. The quoted sentences say what the papers report.
cardiac hypertrophy (548 papers, 2007 to 2026). "Consistently, the ablation of NPPA or NPR1 (the gene encoding NPR-A) as well as NP genetic variants leading to reduced peptide expression have been associated with cardiac hypertrophy and impaired endothelial cell viability and proliferation." (PMID 36982204, 2023). "In addition, we observed that genes associated with cardiac hypertrophy, such as NPPA, NPPB, TNNC1, and DES, were markedly upregulated in the mutant compared with WT iPSC-CMs." (PMID 40779454, 2025). "Notably, NPPA, enriched in DCM, HCM and HIF-1α pathways, encodes atrial natriuretic peptide, which promotes vasodilation and natriuresis to counteract cardiac hypertrophy." (PMID 40597665, 2025). "In addition, studies have also demonstrated that NPPA is implicated in the inhibition of cardiac remodelling and cardiac hypertrophy by inducing cardiomyocyte apoptosis and reducing the growth of cardiomyocytes and fibroblasts." (PMID 34514716, 2021). "Three pro‐hypertrophy markers, namely natriuretic peptide A, natriuretic peptide B and myosin heavy chain beta, are commonly used to evaluate myocardial hypertrophy." (PMID 37985436, 2024). "ChIP-seq further unveiled EBF1 occupancy on promoters of genes linked to cardiac hypertrophy, including MEF2C and NPPA/NPPB." (PMID 39239522, 2024). "These cells also expressed high levels of cardiac hypertrophy and stress‐related (NPPA, NPPB) genes." (PMID 37803909, 2023). "Specifically, established mediators of cardiac hypertrophy such as atrial natriuretic peptide, brain natriuretic peptide and angiotensin-II have shown to increase the ratio of non-myocyte to myocytes." (PMID 36741836, 2022). "In particular, MYRIP was associated with cardiac hypertrophy signaling (e.g., NFAT pathway, NPPA, and NPPB) and aldosterone signaling." (PMID 33679876, 2021). "Upregulated as well is NPPA encoding for atrial natriuretic peptide (ANP), a biomarker for cardiac hypertrophy and heart failure." (PMID 29556499, 2018). "Upregulation of plasma α-l-fucosidase activity was identified as a biomarker candidate for cardiac hypertrophy, which is expected to support the existing marker, atrial natriuretic peptide and its related peptides." (PMID 27281159, 2016). "Fetal genes are a set of genes that are often expressed only in the developing heart and are re-expressed during cardiac hypertrophy, and include natriuretic peptides (NPPA, NPPB), structure proteins (β-MHC, α-skeletal actin) and others." (PMID 26582913, 2016). "We confirmed by qRT-PCR that adult mice have increased levels of mRNA encoding for atrial natriuretic peptide(NPPA) and β-myosin heavy chain (MYH7), two characteristic mRNAs and proteins that increase in cardiac hypertrophy." (PMID 22912742, 2012). "However, under pathological conditions such as cardiac hypertrophy or heart failure, NPPA expression is reactivated in ventricular cardiomyocytes, serving as a biomarker of myocardial stress." (PMID 40869358, 2025). "Additionally, expression levels of natriuretic peptide A (Nppa) and natriuretic peptide B (Nppb), established markers of cardiac hypertrophy and heart failure, were comparable between WT and 582-KO mice." (PMID 41293419, 2025). "IMD treatment significantly reduced fructose-drinking-induced cardiac hypertrophy in rats, as shown by a reduced myocardial cross-sectional area and down-regulated mRNA levels of pro-hypertrophic genes natriuretic peptide A (Nppa) and natriuretic peptide B (Nppb)." (PMID 39338366, 2024). "Cardiac hypertrophy and remodeling are also crucial early adaptative steps (before becoming pathological), which are accompanied by the re-expression of the fetal gene program comprising NPPA, ACTA1, and MYH7." (PMID 37445625, 2023). "NPPA is often considered to be a marker of cardiac hypertrophy, and its elevated levels may be related to worsening cardiac function." (PMID 34497835, 2021).
cardiac hypertrophy (continued). "Several genes, including NPPA (natriuretic peptide A), ACTC1 (alpha-cardiac actin), MYL2 (myosin regulatory light chain 2), and MYL7 (myosin regulatory light chain 7), have been previously implicated in cardiac hypertrophy." (PMID 34422789, 2021). "Pyridostigmine significantly attenuated cardiac hypertrophy based on reduction in left ventricular weight/body weight, suppression of the levels of atrial natriuretic peptide, brain natriuretic peptide and β‐myosin heavy chain, and a reduction in cardiac fibrosis." (PMID 28296184, 2017). "Furthermore, Real-timePCR revealed that cardiac expression of molecular markers of cardiac hypertrophy, such as natriuretic peptide A (Nppa) and B (Nppb), was less pronounced in IF1 KO than in WT mice." (PMID 28874825, 2017). "Furthermore, through Pearson correlation analysis in R, we discovered a significant positive correlation between SSC5D and the cardiac hypertrophy marker genes A-type natriuretic peptide (NPPA) (R = 0.6, p = 3.1e-11) and B-type natriuretic peptide (NPPB) (R = 0.46, p = 1.3e-6)." (PMID 37123263, 2023). "Notably, the NPPA gene is upregulated in ET-1 based in vitro models of cardiac hypertrophy." (PMID 32878883, 2020). "Gene expression of cardiac hypertrophy related genes such as MYH6, TNNT2, NPPA, and NPPB was modestly induced in ISO-treated WT hESC-CMs, but was found to be markedly elevated in MLP KO hESC-CMs." (PMID 31406109, 2019). "Atrial natriuretic peptide (NPPA) and Brain natriuretic peptide (NPPB) are hormones synthesized in the heart that act to inhibit maladaptive cardiac hypertrophy." (PMID 30890961, 2019). "Consequently, the transcription of downstream targets such as NPPA and GATA4 is initiated and pathological cardiac hypertrophy is established." (PMID 26582913, 2016). "Cardiac fetal genes (NPPA, NPPB, MYH6, MYH7 and ACTA1) are usually only expressed during fetal life and re-expression of these genes in adult life is an indicator of pathologic cardiac hypertrophy." (PMID 25051449, 2014). "However, genes associated with cardiac hypertrophy, including GATA4, MYH7, and NPPA, were not differentially expressed in the LV." (PMID 36924351, 2025). "mRNA of natriuretic peptide A (Nppa) but not B (Nppb) was up-regulated in FH hearts, while BNP serum levels were significantly higher in FH than in WN controls, here again confirming pathological cardiac hypertrophy." (PMID 39206703, 2024).
heart failure (365 papers, 2004 to 2026). Inability of the heart to pump blood at an adequate rate to meet tissue metabolic requirements. "Previous studies have also shown that the induction of NPPA in heart failure involves a loss of repressive polycomb marks and a gain in active chromatin marks of the NPPA promoter, including H3K27ac and H3K4me3." (PMID 41526351, 2026). "Consistent with myocardial dysfunction, expression of genes linked to cardiac failure such as Nppa (natriuretic peptide A) and Nppb (natriuretic peptide B) were markedly upregulated in the TAZG197V mice heart samples." (PMID 37533404, 2023). "Over the last four decades, studies have shown that the phenotype associated with NPPA genetic variants and the changes in the circulating levels of ANP reflect its value as a potential therapeutic target for cardiometabolic diseases, including heart failure." (PMID 32670412, 2020). "Importantly, adenoviral overexpression of glypican-6 in cultured cardiomyocytes increased protein synthesis and induced mRNA levels of the pro-hypertrophic signature gene ACTA1 and the hypertrophy and heart failure signature genes encoding natriuretic peptides, NPPA and NPPB." (PMID 27768722, 2016). "Dysregulated gene expression and differential DNA methylation of angiogenic factors may indeed connect heart failure with different etiologies, in the same manner that raised levels of NPPA and the re-induction of a fetal gene programme marks heart failure irregardless of its inciting cause." (PMID 20084101, 2010). "While atrial natriuretic peptide and NT‐proBNP remain established heart failure markers, NT‐proBNP levels fluctuate with infection, renal impairment, and cerebrovascular disease." (PMID 41536841, 2026). "Their results suggest that ADAMTS2 plays a key role in modulating the expression of other heart failure-related genes (including natriuretic peptide A (Nppa) and natriuretic peptide B (Nppb)) in response to isoproterenol treatment." (PMID 40837410, 2025). "Compared with the ISO group, the heart failure marker genes NPPa and NPPb; fibrosis-related gene Postn and hypertrophy-related gene Myh7 also showed clear upregulation in the ISO/PE group." (PMID 40129768, 2025). "Treatment with atrial natriuretic peptide and loop diuretics was started on the same day for heart failure." (PMID 40502903, 2025). "To further explore the effect of WPS on the cardiac functions at the molecular level, we investigated the expression of cardiac failure markers ANP/NPPA and BNP/NPPB in all experimental groups at 72 h post-fertilization." (PMID 34770174, 2021). "For the prediction of a heart failure before it happens, some cardiac markers can be measured includingANP/NPPA and BNP/NPPB." (PMID 34770174, 2021). "The results show that the expression of NPPA was significantly upregulated with heterogeneity in the heart of patients with heart failure in comparison with healthy subjects." (PMID 33854108, 2021). "The ISH results show that the expression of NPPA was significantly upregulated with heterogeneity in the heart of patients with heart failure in comparison with healthy subjects." (PMID 33854108, 2021). "A variant (rs5065) in the coding region of NPPA and an intronic variant (rs1023252) in CLCN6 are associated with NT-pro-BNP levels in severe heart failure patients." (PMID 29302701, 2018). "Notably, heart failure markers such as Cyclin D1 and atrial natriuretic peptide (NPPA) were upregulated in the hearts of obese mice and normalized in the HF + LP group." (PMID 41549510, 2026). "Consistent with the increased heart-to-body-weight ratio of Polg-/mut; Tfam+/+ mice, the expression of Natriuretic Peptide A (Nppa), a marker for heart failure, and Mthfd2 a marker for OXPHOS dysfunction, were increased, whereas there was no change in mRNA levels for Atf4 and Atf5." (PMID 40587199, 2025).